MMP9 (matrix metallopeptidase 9)
Diseases named in the same sentence as MMP9 in open-access papers (continued):
Sharing a sentence is not in itself a finding about the gene and the disease.
ischemic stroke (continued). "Increased peripheral MMP-9 levels have also been reported to be implicated in hemorrhagic transformation after ischemic stroke, ischemic stroke severity and infarct volume, and poor prognosis of AIS." (PMID 36092813, 2022). "One study showed that the MMP-2-735C allele and the MMP-9-1562T allele are independent risk factors that increase the risk of ischemic stroke 1.5 fold compared to other genotypes." (PMID 34445740, 2021). "Whereas, MMP-9 gene-promoter region hypermethylation leads to silencing of the gene and decreases the risk of ischaemic stroke." (PMID 35002488, 2021). "In the present study, we tried to explore the association between MMP-9 polymorphism and methylation in ischaemic stroke patients." (PMID 35002488, 2021). "This study focused on the genetics of the MMP-9 gene polymorphisms and their association with ischaemic stroke." (PMID 35002488, 2021). "Our results revealed that in the case of MMP-9 gene SNP rs3918242 (C→T), subjects with the CT genotypes had 7.09 times higher risk of developing ischaemic stroke compared to the CC genotype." (PMID 35002488, 2021). "aOR for the C allele versus T allele showed that the T allele of the MMP-9 gene added a 10.71-fold risk (aOR = 10.71; 95% CI: 5.65, 21.09; P < 0.001) for the development of ischaemic stroke in our population." (PMID 35002488, 2021). "From this family, two specific variants, MMP-2 and MMP-9, emerge as having a direct link to ischemic stroke." (PMID 34445740, 2021). "MMP-9 is linked to ischemic stroke-induced inflammation and plays a significant role in BBB destruction." (PMID 34299128, 2021). "MMP-9 gene-1562C/T polymorphism (SNP rs3918242) (single-nucleotide polymorphism [SNP] rs3918242) is a potential marker to predict ischaemic stroke and constitutes a significant proportion of the general population." (PMID 35002488, 2021). "Another study showed that the MMP-9 rs3918242 variant has an essential interaction with smoking and increases the risk of ischemic stroke." (PMID 34445740, 2021). "MMP-9 activity is high in the acute phase of an ischemic stroke, which increases the risk of bleeding." (PMID 34299128, 2021). "High MMP-9 levels are associated with increased risk of mortality and major disability in ischemic stroke patients." (PMID 33153204, 2020). "Both TIMP‐1 and MMP‐9 were suggested to have important role in the prognostication of ischaemic stroke, and the coexistence of higher serum TIMP‐1 and MMP‐9 was associated with highest risk of adverse clinical outcomes after ischaemic stroke." (PMID 32431079, 2020). "Some evidence indicates the MMP-9 gene polymorphism associated with the increased risk of ischemic stroke." (PMID 31701356, 2020). "ROC analysis showed that MMP-9 predicted risk for ischemic stroke (AUC = 0.582, 95%CI, 0.510–0.654, P = 0.030)." (PMID 32982940, 2020). "This phenomenon is also known from hemorrhagically transformed ischemic stroke in humans, where an upregulation of MMP-9 has also been linked to disruption of the neurovascular unit." (PMID 30696448, 2019). "The aim of the present study was to investigate the association of six variants in MMP‐9 gene with ischemic stroke severity and the risk for END in ischemic stroke (IS) patients with atrial fibrillation (AF)." (PMID 31012282, 2019). "Ischemic stroke leads to increased MMP-9 (matrixmetalloproteinase-9) levels, causing the breakdown the blood brain barrier (BBB)." (PMID 31795466, 2019). "Matrix metalloproteinase-9 (MMP-9) has been associated with ischemic stroke progression in mouse brain models." (PMID 30237808, 2018). "Hemorrhagic transformation is a major complication of ischemic stroke, is linked to matrix metalloproteinase-9 (MMP-9), and is exacerbated by tissue plasminogen activator (tPA)." (PMID 29617457, 2018). "In patients with ischemic stroke, increased plasma levels of MMP9 and HMGB1 are associated with a poor functional outcome and are significantly correlated with each other." (PMID 28348451, 2017).
ischemic stroke (continued). "Similar findings were observed in a clinical study with the relative increase in MMP-9/TIMP-1 ratio independently associated with symptomatic ICH in ischemic stroke patients." (PMID 26973468, 2016). "In humans with ischemic stroke, early neutrophilia is associated with larger infarct volumes, and MMP-9-positive neutrophil infiltration has also been associated with disruption of the BBB, basal lamina type IV collagen degradation, and HT." (PMID 27561990, 2016). "As such, microvessel inflammation and MMP-9 appear to be key events associated with the development of hemorrhagic complications following ischemic stroke." (PMID 26973468, 2016). "In human ischemic stroke, perivascular neutrophils express MMP-9 and are associated with disrupted micro-vessels, hemorrhagic transformation, and basal lamina degradation." (PMID 26648273, 2015). "In the last years, circulating matrix metalloproteinases (MMP)-9 levels have been associated with functional outcome in ischemic stroke patients." (PMID 26162891, 2015). "The -1562 C/T polymorphism in MMP-9 gene was analyzed in a study of four SNPs in patients with myocardial infarction (854 patients) and those with ischemic stroke (367 patients)." (PMID 26330106, 2015). "The combined IL-18 AA/MMP-9 CT/TT genotypes associated with an increase in risk of composite endpoints (OR = 1.87; 95% CI = 1.13–3.11, p = 0.015, adjusted) and ischemic stroke (OR = 2.54; 95% CI = 1.07–6.00, p = 0.034, adjusted)." (PMID 24040261, 2013). "Thereby, increased MMP-9 levels are associated with haemorrhagic transformation after ischemic stroke." (PMID 23158556, 2012). "MMP-9 is a well-recognized molecule implicated in the proteolytic disruption of the BBB in ischemic stroke." (PMID 22146586, 2011). "Activation of MMP-9 plays an important role in mediating tissue injury during human ischemic stroke and is associated with ICH after t-PA." (PMID 22177314, 2011). "However, one of those meta-analyses showed a significant relationship between the recessive model of the MMP-9-1562C/T polymorphism (TT vs. CC + CT) and the risk of ischemic stroke in the European population (OR 2.06; 95% CI 1.14–3.73; p-value = 0.02)." (PMID 37206663, 2023). "Moreover, the MMP-9/Timp-1 ratio is independently associated with cerebral edema and symptomatic intracerebral hemorrhage in ischemic stroke patients, indicating a critical role for the MMP9/Timp1 ratio in the regulation of BBB integrity." (PMID 37649100, 2023). "Aberrant MMP-9 degrades tight junction and basal membrane proteins, as a result of increased infiltration of inflammatory mediators, which can cause cerebral edema, hinder nutrient exchange, and induce neurotoxicity, thereby exacerbating ischemic stroke." (PMID 35454994, 2022). "Moreover, neutrophile granulocytes have been shown as an important source of MMP-9 that can cause early disruption of the BBB in ischemic stroke." (PMID 36277915, 2022). "MMP-9-positive neutrophils were detected extensively surrounding the cerebral microvessels in the hemorrhagic and infarcted regions of patients with fatal HT after ischemic stroke, which was associated with high MMP9 expression levels and severe basal lamina collagen IV degradation." (PMID 34248961, 2021). "In addition, the MMP-9-1562T genotype has also been proven in studies of both type 2 diabetics and non-diabetics to have a significant association with increased ischemic stroke risk." (PMID 34445740, 2021). "High levels of MMP-9 may predict risk for ischemic stroke in patients with vertigo or dizziness who also have vascular risk factors." (PMID 32982940, 2020). "MMP9 is mainly regulated at the transcriptional level; polymorphisms located in the promoter region have been associated with myocardial infarction, ischaemic stroke, coronary artery disease, lung disorders and a variety of carcinomas (i.e. gastric, breast, urinary)." (PMID 32218930, 2020).
ischemic stroke (continued). "The potential effect of matrix metalloproteinase‐9 (MMP‐9) variants and these variants interactions on hemorrhagic transformation (HT) risk after ischemic stroke (IS) remain unclear." (PMID 31074588, 2019). "However, there are few studies to evaluate the association of MMP‐9 gene polymorphisms with initial ischemic stroke severity and the risk for END IS patients with AF." (PMID 31012282, 2019). "With this background we aimed to investigate whether MMP‐9 gene polymorphisms influence initial ischemic stroke severity and the risk of END in acute IS patients with AF in the Chinese population." (PMID 31012282, 2019). "MMP-9 may mediate tissue injury caused by human ischemic stroke and links with intracranial hemorrhage transformation due to thrombolytic therapy." (PMID 30619060, 2018). "Several studies suggest MMP-9 may play a more prominent role in BBB disruption during ischemic stroke under clinical conditions linked to elevated systemic inflammation." (PMID 23565108, 2013). "pGSN is cleaved in vitro by MMP-3, MMP-2, MMP-1, MMP-14 and MMP-9 which may be the cause of the severe depletion of pGSN observed in patients who suffer ischemic stroke." (PMID 22047744, 2011). "Thus, studies have demonstrated that a panel of biomarkers, including complement C3, high-sensitive C-reactive protein, hepatocyte growth factor, MMP9, and anti-phosphatidylserine antibodies, can provide more comprehensive risk stratification for adverse outcomes in ischemic stroke." (PMID 39459548, 2024). "Further, butyrate, as well as fecal butyrate-producing bacteria, has been shown to reduce the activity of MMP-9 in a diabetic mouse model of ischemic stroke." (PMID 40332093, 2025). "Combined treatment with baicalin and t-PA leads to a decrease in MMP-9 levels, thereby reducing the incidence of ischemic stroke." (PMID 40565017, 2025). "LXA4 ME also decreased the permeability of the blood–brain barrier after ischemic stroke by upregulating tissue metallopeptidase inhibitor-1 and downregulating matrix metallopeptidase 9 (MMP-9)." (PMID 40862723, 2025). "Exercise preconditioning strengthens the basal lamina and reduces blood-brain barrier (BBB) dysfunction in ischemic stroke by increasing MMP-9." (PMID 40520194, 2025). "Nobiletin improves vascular function and downregulates the expression of MMP-2, MMP-9, and ischemic stroke severity." (PMID 40565017, 2025). "RF maintains the BBB integrity following ischemic stroke by reducing neutrophil infiltration and the subsequent release of MMP9, thereby alleviating both neurological and histological impairments." (PMID 39915908, 2025). "Previous study in ischemic stroke has demonstrated that FABP4 activation can upregulate MMP-9 to disrupt tight junctions and exacerbate BBB injury." (PMID 41204337, 2025). "Ischemic stroke induced by focal Middle Cerebral Artery occlusion (MCAO) resulted in a significant increase in MMP-9 levels in the cerebral cortex of the ipsilateral hemisphere compared to the sham group." (PMID 38255970, 2024). "MMP-9 activation plays a significant role in the pathogenesis of a wide range of central nervous system disorders, such as ischemic stroke, meningitis, and encephalitis." (PMID 39457496, 2024). "Matrix metalloproteinases (MMPs) such as MMP-9, 3, and 2 degrade the cellular matrix and are believed to play a crucial role in ischemic stroke." (PMID 39273389, 2024). "As with ischemic stroke, the application of specific MMP-9 inhibitors to these conditions will require greater knowledge of time-dependent expression and function during the disease process." (PMID 39273389, 2024). "Minocycline is known for its MMP-inhibitory effect in neurological diseases; a clinical trial showed that minocycline administration decreased plasma MMP-9 levels in patients with ischemic stroke." (PMID 39766566, 2024).
ischemic stroke (continued). "Our study shows changes in MMP-9 activity levels using a gel zymography approach, following ischemic stroke induced by focal Middle Cerebral Artery occlusion (MCAOMCAO)." (PMID 38255970, 2024). "In cases of ischemic stroke, MMP-9 inhibitors have been shown to specifically reduce the levels of MMP-9, inflammation, and activation while improving neurological function." (PMID 39712025, 2024). "We assessed neurological deficits, infarct volume, blood–brain barrier (BBB) permeability, TNF-alpha levels, total oxidant capacity, and gene expressions that play a role in BBB integrity (VEGF, Occludin, and MMP-9) following ischemic stroke." (PMID 39309404, 2024). "We conclude that in experimental ischemic stroke with reperfusion, the duration of ischemia and r-tPA treatment significantly altered MMP-9, 3, and 2 expression, ischemic brain injury, and neurological disability." (PMID 39273389, 2024). "In summary, the results presented herein suggest a dynamic and time-dependent regulation of MMP-9 activity in response to ischemic stroke, highlighting its potential significance in the acute and recovery phases of cerebral ischemia." (PMID 38255970, 2024). "In summary, in experimental ischemic stroke in male mice with reperfusion, the duration of ischemia, and r-tPA treatment significantly altered the immunofluorescent expression of MMP-9, 3, and 2, ischemic brain injury, and neurological disability." (PMID 39273389, 2024). "We found that ischemic stroke resulted in a significant increase in MMP-9 levels in the cerebral cortex of the ipsilateral hemisphere compared to the sham group." (PMID 38255970, 2024). "The major findings of this study can be summarized as follows: Ischemic stroke evokes significant increases in MMP-9 activity in the ipsilateral cortex and hippocampus during first 24 h after the injury." (PMID 38255970, 2024). "Examination of the activity of MMP-2 and MMP-9 in protein extracts from human brain tissue at different time points after ischemic stroke revealed a transient dependence during the course of pathology." (PMID 37511788, 2023). "Previous studies reported that IL-1, which increased after ischaemic stroke or other risk factors, targeted astrocytes and increased the expression of IL-6, TNF-a, MMP-9, and chemokines." (PMID 36600830, 2023). "In ischemic stroke models, MMP‐9 KO mice have less BBB damage and smaller strokes, and MMP inhibitor‐treated rats have reduced infarct size." (PMID 37452512, 2023). "In ischemic stroke, MMP‐9 activates proinflammatory cytokines and chemokines, such as CXCL8, IL‐1β, and TNF‐α." (PMID 37452512, 2023). "A previous study claimed that NBP protected BBB integrity and attenuated brain injury in the acute phase of ischemic stroke by decreasing MMP‐9 enzyme activity." (PMID 36756709, 2023). "These authors noted decreased levels of interleukin-1 (IL-1b) and matrix metallopeptidase 9 (MMP 9) in the periinfarct area of mice suffering from ischemic stroke." (PMID 37388676, 2023). "Previous studies documented that MMP-2 and MMP-9 are essential in BBB disruption during ischemic stroke." (PMID 37955765, 2023). "Given their significant role in BBB disruption, MMPs, especially MMP-9, have become therapeutic targets for interventions aiming to reduce the complications of ischemic stroke." (PMID 38178909, 2023). "MiR-212 suppressed matrix metallopeptidase 9 to block the Notch signaling pathway, thus promoting the regeneration of vascular tissue and endothelial cell function after ischemic stroke." (PMID 38057703, 2023). "The aim of our research was to analyze non-specific laboratory data, including admission laboratory parameters, as well as baseline levels of MMP-2 and MMP-9 in the serum of patients with ischemic stroke." (PMID 37675160, 2023). "It was found that MMP-2 is the initiator of BBB derangement following cerebral ischemia, while MMP-9 is the principal contributor to BBB dysregulation in the delayed phase after ischemic stroke." (PMID 37955765, 2023).
ischemic stroke (continued). "As MMP-9 was the primary proteolytic enzyme, which was reported to degrade claudin-5 and ZO-1 after ischemic stroke, Con-exo significantly inhibited the level of MMP-9 compared with the MCAO group (P < 0.01)." (PMID 35308117, 2022). "MMP9 is upregulated during ischemic stroke, intracerebral hemorrhage (ICH), and SCI, and is highly relevant to thrombin enrichment in spinal parenchyma." (PMID 35842640, 2022). "This study shows that the presence of one MMP9 SNP and one MMP SNP‐SNP interaction increase the risk for ischemic stroke in the Han Hakka population." (PMID 34984852, 2022). "The NF-κB/MMP-9 signaling pathways contribute to the degradation of claudin-5, prompting hemorrhagic transformation in ischemic stroke." (PMID 35456999, 2022). "Thrombolytic therapy increased the levels of NT and MMP-9 in the plasma of ischemic stroke patients." (PMID 35477576, 2022). "The plasma MMP-9 level has been used as a biomarker to predict hemorrhagic transformation in ischemic stroke with thrombolytic treatment." (PMID 35814200, 2022). "Among all MMP subtypes, MMP-2 and MMP-9 have been the most investigated in ischemic stroke, with MMP-9 being reported as the principal culprit in the disruption of BBB and neuronal damage." (PMID 35454994, 2022). "Some researchers have shown that PEMF significantly decreased inflammatory IL-1β and MMP-9 in the ischemic stroke brain." (PMID 35163096, 2022). "In RT-PCR assays, mRNA levels of TNF-α, IL-1β, MMP-2, and MMP-9 were remarkably elevated following ischemic stroke." (PMID 36186136, 2022). "In particular, MMP-9 was found to be significantly increased in postmortem brain tissues obtained from patients with ischemic stroke, and was shown to be mainly localized in infiltrating neutrophils, endothelial cells, and activated microglia." (PMID 35454994, 2022). "MMP9 also exacerbates injury pathways in ischemic stroke, impairs and actively degrades components of the BBB, leading to the development of cerebral edema and hemorrhagic transformation." (PMID 39086962, 2022). "MMP-9 (gelatinase B, 92-kDa collagenase) is a well-studied enzyme in ischemic stroke, and its expression is rapidly upregulated after cerebral ischemia." (PMID 36699006, 2022). "Ischemic stroke stimulated activation of the CPECs apical membrane SPAK–NKCC1 complex, NF-κB, and MMP9, which was associated with loss of the blood–CSF barrier integrity and increased immune cell infiltration into the ChP." (PMID 35413993, 2022). "During ischemic stroke, a large amount of plasmin, hydrolase, and free radicals are released, subsequently activating MMP-9 and aggravating ischemic brain injury." (PMID 35814200, 2022). "MMP-9, which is mainly derived from infiltrated neutrophils and inflammation-activated endothelial cells during ischemic stroke, plays a critical role in the delayed tPA-induced BBB disruption, hemorrhagic transformation, and neuroinflammation." (PMID 35309561, 2022). "For examples, our previous study showed that baicalin attenuated the BBB disruption and hemorrhagic transformation, and improved neurological outcome in ischemic stroke rats with delayed t-PA treatment via inhibiting ONOO−/MMP-9 signaling pathway." (PMID 35477576, 2022). "In our study, we detected increased NF-κB pathway activation and MMP9 protein expression in ChP from ischemic stroke brains, which likely contributes to damage to the ChP barrier integrity." (PMID 35413993, 2022). "We reported here that ischemic stroke stimulated phosphorylation activation of SPAK–NKCC1 cascade at the apical membrane of CPECs, which was associated with upregulation of NF-κB, MMP9 and loss of TJs integrity as well as immune cell infiltration in the ChP." (PMID 35413993, 2022). "It has also been suggested that MMP9 is related to the inflammation induced by ischemic stroke and participates in the destruction of the BBB." (PMID 36061592, 2022).